TNF (tumor necrosis factor)
Diseases named in the same sentence as TNF in open-access papers (continued):
Sharing a sentence is not in itself a finding about the gene and the disease.
Graves ophthalmopathy (9 papers, 2013 to 2025). An autoimmune disorder of the EYE, occurring in patients with Graves disease. "The present study aims to explore the correlation of human leucocyte antigen (HLA)-DQ and tumour necrosis factor (TNF)-α gene polymorphisms with ocular myasthenia gravis (OMG) combined with thyroid-associated ophthalmopathy (TAO)." (PMID 28119492, 2017). "Distribution of HLA DRB1*03 and TNF polymorphisms in GD patients stratified by the diagnosis of Graves’ ophthalmopathy." (PMID 23544060, 2013). "Recent studies have shown that laduviglusib can inhibit the activation of Akt, PI3K, nuclear factor-κB induced by IL-1β and TNF-α in cells modeling Graves’ orbitopathy." (PMID 38918688, 2024). "CXCR6 was upregulated in the primary culture of orbital fibroblasts from patients with Graves’ orbitopathy, following treatment with pro-inflammatory cytokines IL-1β and TNF-α." (PMID 36658547, 2023). "It is also possible that the increased levels of CD40L seen in our model stimulate a proinflammatory fibrocyte phenotype characterized by secretion of TNF-α as has been recently described in the setting of Grave's ophthalmopathy, though this hypothesis will require more evaluation." (PMID 24904415, 2014).
Hyponatremia (9 papers, 2013 to 2025). An abnormally decreased sodium concentration in the blood. "IL-6, TNF-α as well as other cytokines participate in inflammation of KD patients in the acute phase, suggesting that hyponatremia may be associated with inappropriate release of ADH." (PMID 31921727, 2019). "Lipopolysaccharide (LPS) and inflammatory mediators (such as IL-1β, IL-6, and TNF-α) contribute to the pathogenesis of hyponatremia." (PMID 40636392, 2025). "In this case, the cytokine levels of G-CSF and TNF-α produced by PBMC following LPS stimulation differ among septic patients with hyponatremia, eunatremia, and hypernatremia." (PMID 37425258, 2023). "The differences in day 1 G-CSF and TNF-α response after LPS stimulation among patients with hyponatremia, eunatremia, and hypernatremia were significant (p = 0.020 and 0.010, respectively)." (PMID 36140385, 2022). "To this end, we measured TNFα and Il6 levels in hyponatremia patients." (PMID 37992803, 2023). "Additionally, CY might cause hyponatremia by upregulating expression of ADH receptor V2R and aquaporin 2 through suppression of interleukin-1 and tumor necrosis factor-α, which act as negative regulators of VR2 expression." (PMID 33235058, 2020). "Plasma IL-6 and TNF-α levels are significantly increased in IVIG-resistant children, which can explain the significant hyponatremia and can also serve as a predictor of IVIG-resistant KD." (PMID 36964445, 2023). "The marked increase in plasma IL-6 and TNF-α in IVIG-resistant infants compared with IVIG-responsive patients may explain the significant hyponatremia in IVIG non-responders." (PMID 31921727, 2019).
hypovitaminosis D (9 papers, 2012 to 2023). "The association between hypovitaminosis D and increase in levels of TNF-α in patients with HAM/TSP may suggest vitamin D is involved in the pathogenesis of neurological disease caused by HTLV-1." (PMID 34835029, 2021). "Patients with HAM/TSP and hypovitaminosis D had higher levels of TNF-α than asymptomatic HTLV carriers." (PMID 34835029, 2021). "Hypovitaminosis D increases the expression of inflammatory cytokines such as tumor necrosis factor-α (TNF-α), increasing the expression of the InsP3Rs and resulting in increased intracellular Ca2+ and accelerating cellular damage, apoptosis, and aging." (PMID 31083546, 2019). "The mRNA levels of TG2 and TNF-α were higher in PBMC of subjects having hypovitaminosis D, namely plasma 25(OH)vitamin D3 levels lower than 50 nmol/L, than in those with normal vitamin D levels." (PMID 30453584, 2018). "In this study, high mRNA levels of TG2 and TNF-α were found in subjects with hypovitaminosis D, namely serum 25(OH)vitamin D3 levels lower than 50 nmol/L, according to the estimated current cut-off value." (PMID 30453584, 2018). "HTLV-infected patients with hypovitaminosis D had significantly higher levels of IL-6 (95 pg/mL; IQR: 36–119) and TNF-α (50 pg/mL; IQR: 24.3–94.2) than patients with normal vitamin D levels (IL-6: 57 pg/mL; IQR: 31.4–99; p < 0.001; TNF-α: 40.3 pg/mL, IQR: 6.8–62.8; p = 0.001)." (PMID 34835029, 2021).
ileus (9 papers, 2013 to 2023). Decrease in peristalsis in the absence of a mechanical bowel obstruction. "The pro-inflammatory cytokines TNF-α and IL-6 in adipose tissue and liver in obese mice fed a high-fat diet and the levels of TNF-α and IL-6 in postoperative ileus rats can be reduced by ginsenoside Rb1." (PMID 32020864, 2020). "In a rat with postoperative ileus, ginsenoside Rb1 reduces serum concentration of TNF-α, IL-1β, IL-6, and IL-10, indicating its anti-inflammatory effect." (PMID 30402203, 2018). "In rats with postoperative ileus, expression of TNF-α, IL-1β, IL-6, and IL-10 is reduced by Rb1 in ileum tissue, along with gastrointestinal transit increased, indicating a potent anti-inflammatory effect." (PMID 30402203, 2018). "By supplementing with probiotics or synbiotics before and after the operation, it is possible to alleviate post-operative ileus by reducing the levels of pro-inflammatory molecules such as tumor necrosis factor-α, interleukin-6, C-reactive protein, and nitric oxide." (PMID 37373843, 2023). "The local inflammatory status may have a significant modulating role and correlations between ileus and increased systemic levels of proinflammatory cytokines (IL-1β, IL-6 and TNF-α) were also identified." (PMID 24137421, 2013). "In the postoperative ileus (POI) model, EA at ST36 decreased TNF-α and IL-6 concentration in serum and MPO activities in the intestine." (PMID 35095910, 2021). "TNF-α was also significantly higher in patients who developed prolonged POI after colorectal surgery compared to patients who did not develop ileus." (PMID 35805922, 2022). "Of note, changes in TNF expression do not coincide with the onset of ileus in a mouse (C57Bl/6) gut manipulation model of ileus (in this case, ileus is attributed to TH1 cytokines)." (PMID 35805922, 2022). "Previously, we indeed demonstrated that nicotine failed to reduce TNF-α production in peritoneal macrophages of α7 nAChR knockout mice, whereas the anti-inflammatory effect in the small intestine of vagus nerve stimulation in our model of postoperative ileus is lost in these KO mice." (PMID 24223920, 2013). "Investigations into the role of inflammatory mediators in the development of ileus have been somewhat biased, in that most investigators check a handful of classic inflammatory mediators, such as IL6 and TNF-α, without examining other inflammatory mediators." (PMID 35805922, 2022).
intestinal cancer (9 papers, 2017 to 2025). "Previously, in a mouse model of intestinal cancer, sunitinib administration at a dosing protocol of 30 mg/kg every other day for 9 weeks resulted in a reduction in various inflammation-related factors, such as IL-6, IL-1α/1β, TNFα, and IFN-γ at the mRNA level within the GI tract." (PMID 38339116, 2024). "These recent genetic studies are consistent with the demonstration of enhanced NOX1 expression in vitro following exposure of intestinal cancer cells to the pro-inflammatory cytokines interferon-γ [IFN-γ] and tumor necrosis factor-α [TNF-α]." (PMID 28498822, 2017). "In the treatment of intestinal cancer, some studies have concentrated on the combination of TNF inhibitors and immune checkpoint inhibitors (e.g. PD-1/PD-L1 antibodies), given the pro-M2 effect of TNF-α in the tumor microenvironment." (PMID 40109347, 2025).
intestinal obstruction (9 papers, 2012 to 2025). Blockage of the normal flow of the intestinal contents within the bowel. "Intestinal obstruction led to significant changes in IL-2 and TNF-α compared with the normal control group." (PMID 28953987, 2017). "IL-2 was increased after relieving the intestinal obstruction, while TNF-α was decreased." (PMID 28953987, 2017). "TNF-α-mediated mSCF down-regulation is not the only reason of partial intestinal obstruction-induced loss of ICC." (PMID 23133623, 2012).
intestinal tumors (9 papers, 2015 to 2025). "In intestinal tumors, TNF-α disrupts interactions between IDH1 and the deacetylase SIRT1, leading to decreased IDH1 protein stability." (PMID 40906076, 2025). "The results found that PZH not only inhibited the increase in the number and volume of intestinal tumors in CAC mice but also suppressed the secretion of pro-inflammatory cytokines IL-6, TNF-α, and IL-1β in mouse serum." (PMID 39020410, 2024).
intracranial aneurysm (9 papers, 2014 to 2025). "A histopathologic analysis of a different intracranial aneurysm that was later resected yielded a diagnosis of polyarteritis nodosa and positive staining for TNFα." (PMID 34887823, 2021). "The role of TNF-α as a pro-inflammatory biomarker and its relationship to the growth and rupture of intracranial aneurysms is already widely known and described in the literature." (PMID 31915532, 2019). "Treatment with a TNF-α inhibitor in vivo could reverse aneurysmal change during the formation of intracranial aneurysms." (PMID 36452231, 2022). "Owens GK and his colleagues demonstrated that TNF-α could promote VSMCs pro-inflammatory/matrix-remodeling phenotype and accelerate the formation of intracranial aneurysms." (PMID 36452231, 2022). "TNF-α is an inflammatory biomarker related to the presence and rupture of intracranial aneurysms and its receptor, TNFR1, could be detected in peripheral blood." (PMID 31915532, 2019). "Third, because of the limited intracranial aneurysm tissue available, the immunohistochemical confirmation of the hypotheses generated in silico are limited to inflammation in the aneurysm wall and positive staining for TNFα and NFκB." (PMID 34887823, 2021). "Experimental animal studies have shown that intracranial aneurysm formation, progression, and rupture could be mitigated by inhibiting SASP factors such as IL‐1β, TNF‐α, MCP‐1, and MMPs." (PMID 41026146, 2025). "Our study showed that there was no significant elevation in TNF serum levels following intracranial aneurysm stenting, suggesting that performed procedures did not induce TNF-mediated processes including neuroapoptosis and BBB disruption." (PMID 37759909, 2023).
laryngeal carcinoma (9 papers, 2009 to 2025). Carcinoma that arises from the laryngeal epithelium. "TNF-α (tumor necrosis factor alpha) has been confirmed to promote tumor growth in laryngeal carcinoma." (PMID 34199169, 2021). "Examination of serum CCL2 and TNF-α in 297 patients with pretreatment laryngeal cancer showed that CCL2 and TNF-α levels were independent predictors of overall survival and distant metastasis-free survival." (PMID 33297571, 2020). "This study was aimed to investigate the effect of combined cancer gene therapy with exogenous tumor necrosis factor-alpha (TNF-α) and cytosine deaminase (CD) suicide gene on laryngeal carcinoma cell line Hep-2 in vitro and in vivo." (PMID 23593411, 2013). "We assessed the serum levels of cytokines (IL–1, IL–2,IL–4, IL–6, IL–8, IL–10, IFN–gamma, TNF–alpha, GM–CSF), chemokines (MCP–1 and MIP–1alpha)and growth factors (VEGF and bFGF) in laryngeal cancer patients before, during and after surgery." (PMID 20108543, 2009).
leukocytoclastic vasculitis (9 papers, 2014 to 2025). "Several case reports and systematic reviews have implicated TNF-α inhibitors, including adalimumab, in the development of leukocytoclastic vasculitis and IgA vasculitis." (PMID 41567199, 2025). "While most cases of biologic-associated LCV are induced by TNF-α inhibitors, only two known cases of tocilizumab-induced hypersensitivity vasculitis have been published in the literature." (PMID 41333011, 2025). "It revealed only two case reports of tocilizumab-induced hypersensitivity vasculitis, while most cases were linked to TNF-α inhibitors." (PMID 41333011, 2025). "Leukocytoclastic vasculitis (LCV) is a known hypersensitivity reaction to biologic agents, often linked to tumor necrosis factor-α (TNF-α)inhibitors." (PMID 41333011, 2025). "The most common histopathological type of anti-TNF-α related vasculitis was leukocytoclastic vasculitis and the most common area of involvement was skin." (PMID 25133007, 2014).
lung squamous cell carcinoma (9 papers, 2020 to 2024). "MAP3K14 has been found to be differentially expressed and hypermethylated in lung squamous cell carcinoma, where it regulates the NF-κB activity pathway and participates in NF-κB-inducing signaling through receptors of the tumor-necrosis/nerve-growth factor (TNF/NGF) family." (PMID 37628872, 2023).
meningioma (9 papers, 2014 to 2025). A generally slow growing tumor attached to the dura mater. "Given the same putative drivers of disease associations, Fostamatinib may improve meningioma via regulating synthesis and secretion of tumor necrosis factor α(TNF-α)." (PMID 32983987, 2020). "DEGs of MYC and CXCL8, miRNAs of miR-29c-3p and miR-145-5p, as well as pathways such as the TNF signaling pathway, cytokine-cytokine receptor interaction, and IL-17 signaling pathway, probably involved in meningioma development, were obtained." (PMID 34772393, 2021). "Hence, we speculate that the key genes, including MYC and CXCL8, are involved in meningioma progression via the regulating of different pathways such as the TNF signaling pathway, cytokine-cytokine receptor interaction, and IL-17 signaling pathway." (PMID 34772393, 2021). "Those most investigated with respect to seizures and meningioma include IL‐1ra, IL‐1β, IL‐6, IL‐10, IFN‐γ, and TNF‐α." (PMID 40729436, 2025). "Other cytokines expressed in meningioma such as IL‐1β, IL‐1α, and TNF‐α have not had corresponding receptors detected yet." (PMID 40729436, 2025). "It has been reported that the most abundant cytokines in meningiomas are IFN-γ, TNF-α, and TGF-β." (PMID 37368708, 2023). "Similarly, it has been found that CXC receptor activates ERK1/2 and stimulates meningioma cell proliferation, and in systematic investigation of quercetin for cardiovascular disease treatment, CXCL8 is enriched in the TNF signaling and IL-17 signaling pathways." (PMID 34772393, 2021).
panuveitis (9 papers, 2018 to 2025). A disorder characterized by inflammation of the entire uvea which includes the iris, ciliary body, and choroid. "Panuveitis seemed to be more often associated with anti-TNFα treatment [OR = 9.17 (2.23–37.60), p = 0.0021]." (PMID 35311049, 2022). "In this context, a clinical phase I/II study is worth mentioning, which is carrying out electro-transfection of the ciliary muscle, encoding the soluble human TNF-a p55 receptor in patients with posterior, intermediate and panuveitis (NCT03308045)." (PMID 33634341, 2021). "One of them also had relapsing panuveitis, which did not respond to topical steroids or to two anti-TNFα agents." (PMID 37509600, 2023). "Adalimumab, a fully humanized monoclinal anti-TNF-α antibody, has been approved for the treatment of non-infectious intermediate, posterior, and panuveitis in adults and pediatric patients 2 years of age and older by the Food and Drug Administration." (PMID 36431163, 2022).
pemphigus vulgaris (9 papers, 2008 to 2025). Pemphigus is a group of chronic autoimmune skin diseases characterized by blister formations on the outer layer of the skin and the mucous membranes. "As most studies on pemphigus vulgaris (PV) pathogenesis concern its active stage, we aimed to evaluate the serum concentration of TNF-α, IL-1, and IL-6 in PV patients in clinical remission." (PMID 18584045, 2008). "Data support the role of cytokines IL-1 and TNF-α in the pathogenesis of pemphigus vulgaris." (PMID 35372527, 2022). "As the concentration of TNF-α in the local skin lesions is elevated, inhibition of TNF-α by infliximab or etanercept could be a successful treatment for pemphigus vulgaris in a few studies." (PMID 35783635, 2022).
polyp (9 papers, 2009 to 2024). A usually exophytic mass attached to the underlying tissue by a broad base or a thin stalk. "The presence of aberrant crypt foci (ACF) in the polyp group was associated with higher tumor necrosis factor-alpha (TNF-α) concentrations." (PMID 38003638, 2023). "The prostaglandin E2 (PGE2), TNF-α, and IL-8 contents in polyp tissues were detected using enzyme-linked immunosorbent assay." (PMID 30040868, 2018). "Of the adipokines associated with polyp number or type, including IP-10, TNF-α and leptin, all are considered pro-inflammatory at elevated concentrations and increase the activity of signaling pathways in their target cells." (PMID 24465801, 2014). "Two adipokines (leptin and IP-10) were the same as for polyp number, and additionally, TNF-α had a statistically significant association with the presence of a tubular adenoma." (PMID 24465801, 2014). "In this study, the concentrations of IL-8 and TNF-α in polyp tissues from smoking CRSwNP patients were significantly higher compared with those in nonsmoking CRSwNP patients." (PMID 30040868, 2018). "The values of PGE2, TNF-α, and IL-8 in the polyp tissues were significantly higher in smoking CRSwNP patients than those in nonsmoking CRSwNP patients." (PMID 30040868, 2018). "CS exposure downregulates the expression levels of EP2 and EP4 receptors and stimulates the production of PGE2 and the proinflammatory cytokine IL-8 and TNF-α in polyp tissues of CRS patients." (PMID 30040868, 2018). "Significant associations were observed between two of these serum adipokines (leptin and IP-10) with polyp number, and a third serum adipokine (TNF-α) showed a trend towards significance (p = 0.09)." (PMID 24465801, 2014). "Nasal polyp fibroblasts were cultured alone or with IL-17A (10 ng/mL) and TNF-α (10 ng/mL), alone and in combination." (PMID 23283206, 2009). "This may explain why the highest level of IELs were found among polypoid colons in the present study, whereas the lowest polyp formation by ST4 may be due to its downregulation of TNF-α." (PMID 36380160, 2023). "This hypothesis is supported by earlier findings showing that intestinal MCs are an important source of TNF-α with which they are involved in a progressive epithelial transformation and polyp development." (PMID 37730723, 2023). "The quintessential cancer-associated cytokine, TNF-α was strongly associated with the presence of a tubular adenoma but not with polyp number in our study population." (PMID 24465801, 2014). "For patients with JPS polyps, our study identifies several potential approaches, including anti‐TNF, anti‐CD44 and anti‐VEGF therapies, to reduce polyp recurrence after polypectomy or serve as palliative treatments if polypectomy is not feasible." (PMID 38264936, 2024).